GLP1R (glucagon like peptide 1 receptor)
Diseases named in the same sentence as GLP1R in open-access papers (continued):
Sharing a sentence is not in itself a finding about the gene and the disease.
nonalcoholic fatty liver (1 paper, 2020). "Moreover, GLP-1R agonists stimulate ANGPTL8 production in human hepatocytes dose-dependently, and ANGPTL8 has been described as a novel vitamin D receptor target gene involved in nonalcoholic fatty liver pathogenesis." (PMID 32746907, 2020).
ovarian dysfunction (1 paper, 2023). The inability of the ovaries to function. "Therefore, we performed a protocol for systematic review and meta-analysis to investigate the efficacy and safety of glucagon-like peptide-1 receptor agonists on ovarian dysfunction in PCOS." (PMID 36637917, 2023).
ovarian tumor (1 paper, 2020). "In contrast, few studies have been conducted focusing on GLP-1R expression in the ovary with an exception that reported the GLP-1R is expressed in human ovarian tumor cells." (PMID 32655632, 2020).
parasitic infections (1 paper, 2025). "Therefore, it is critical to understand the GLP-1/GLP-1R axis in eosinophils along with other immune cells to delineate the pathogenesis of eosinophil-mediated adverse events in patients undergoing GLP-1RA-based therapies and its use during parasitic infections." (PMID 40592472, 2025).
partial lipodystrophy (1 paper, 2024). Loss and redistribution of subcutaneous and/or visceral adipose tissue from specific regions of the body. "Indeed, the case reports that exist do suggest that GLP-1R agonists can be beneficial in individuals with partial lipodystrophy." (PMID 38745956, 2024).
prion disease (1 paper, 2019). A transmissible disease that is caused by a protein that is able to induce abnormal folding of normal cellular proteins, leading to characteristic spongiform brain changes, which are associated with neuronal loss without an inflammatory response. "To determine, if GLP-1R up-regulation also plays a role in prion diseases, and is targeted by our knockout strategy, we assessed levels of GLP-1R in brain homogenates from terminally prion diseased TKO- and WT-mice and their non-infected age-matched controls." (PMID 31118110, 2019). "Since GLP-1R is considered to be a microglia marker, we propose that microglia dysregulation in prion diseases might be very distinct from that in other neurodegenerative diseases." (PMID 31118110, 2019). "Since GLP-1R was found to be significantly changed in TKO-mice at clinical prion disease, we asked whether microglia homeostasis was disturbed earlier in the prion infected TKO-mice." (PMID 31118110, 2019). "Therefore, GLP-1R reducing strategies might probably be unsuitable as a therapeutic option in prion diseases." (PMID 31118110, 2019).
prostate adenocarcinoma (1 paper, 2020). "With generally only 5% expression of GLP-1R on prostate adenocarcinoma, GLP-1RA was likely to repress the development of prostate neoplasm beyond GLP-1R." (PMID 33424764, 2020).
skin cancer (1 paper, 2024). "Insufficient evidence was found for the associations between genetically proxied GLP1R, KCNJ11, ABCC8, and PPARG perturbations and skin cancer risk." (PMID 39640975, 2024).
ST Elevation Myocardial Infarction (1 paper, 2025). A myocardial infarction that produces elevation in the ST segments of the ECG. "This scoping review synthesizes current evidence on glucagon-like peptide-1 receptor agonist (GLP-1RA) use after ST-elevation myocardial infarction (STEMI), highlighting their potential as adjunctive therapy." (PMID 41230336, 2025).
temporal lobe epilepsy (1 paper, 2024). A localization-related (focal) form of epilepsy characterized by recurrent seizures that arise from foci within the temporal lobe, most commonly from its mesial aspect. "Background/Objectives: Glucagon-like peptide-1 receptor agonists such as liraglutide are known for their neuroprotective effects in neurodegenerative disorders, but their role in temporal lobe epilepsy (TLE) remains unclear." (PMID 39457518, 2024).
thrombotic disease (1 paper, 2016). The formation of a blood clot in the lumen of a vessel or heart chamber; causes include coagulation disorders and vascular endothelial injury. "Another cost-effective strategy may be to repurpose already-established drugs by discovering novel mechanisms of action in anti-thrombotic diseases, such as the recently-identified GLP-1R agonist, Exenatide, an anti-diabetic drug that has potential anti-thrombotic effects." (PMID 27766055, 2016).
viral hepatitis (1 paper, 2024). An acute or chronic inflammation of the liver parenchyma caused by viruses. "We performed this research to compare the risks of cardiovascular diseases, cirrhosis, liver-related mortality, and cardiovascular mortality between glucagon-like peptide-1 receptor agonist (GLP-1 RA) use and no-use in patients with T2D without viral hepatitis." (PMID 38172833, 2024).
viral infections (1 paper, 2025). "Therefore, it is critical to understand the role of GLP-1 in bacterial and viral infections to target the GLP-1/GLP-1R axis for increasing the efficacy of available therapeutics, specifically for sepsis management." (PMID 40592472, 2025).
cardiovascular disease (138 papers, 2010 to 2026). "Recent clinical trials have demonstrated beneficial effects GLP-1R agonists on renal outcomes, especially in patients with T2D who are at high risk for developing cardiovascular disease." (PMID 35884965, 2022). "Several large cardiovascular outcome trials have demonstrated that glucagon-like peptide-1 receptor agonists (GLP-1 RAs) reduce the risk of cardiovascular disease in type 2 diabetes." (PMID 34441365, 2021). "A GLP1R natural missense variant, A316T, protects against T2D and cardiovascular disease." (PMID 41637494, 2026). "In addition, GLP-1R is highly expressed in the heart, and prominent in the therapeutics of T2D due to their efficacy in glycemia, safety, low risk of hypoglycemia and multilevel pathophysiological superiority and benefits in cardiovascular disease reduction." (PMID 33397369, 2021). "This broad distribution underscores the pleiotropic effects of GLP-1 and provides the anatomical basis for the therapeutic benefits of GLP-1R agonists in metabolic and cardiovascular disease." (PMID 41303737, 2025). "Glucagon-like peptide-1 receptor agonist(GLP-1RA) is commonly used in patients with cardiovascular disease due to its significant improvement in the prognosis of atherosclerotic cardiovascular disease (ASCVD)." (PMID 38559688, 2024). "The indication was later confirmed by the 2021 ESC Guidelines on cardiovascular disease prevention (i.e. class I indication for GLP1-R in patients with DM2 and atherosclerotic cardiovascular disease to reduce CV and cardiorenal outcomes)." (PMID 38468245, 2024). "A comprehensive understanding of these pathways and their interplay with GLP1R is pivotal for identifying novel therapeutic targets and for devising strategies with potential clinical applications in diverse cardiovascular diseases, particularly DCM." (PMID 38543160, 2024). "Newer glucose-lowering agents such as glucagon-like peptide 1 receptor agonists (GLP-1 RA) or sodium-glucose-like cotransporter 2 inhibitors (SGLT2i) have established cardiovascular disease benefits." (PMID 38812009, 2024). "The publication of two critical studies has also delivered on the promise of GLP-1R imaging in cardiovascular disease." (PMID 37780209, 2023). "Sodium glucose cotransporter 2 inhibitors (SGLT2i) and glucagon-like peptide-1 receptor agonists (GLP-1RAs) have been shown to improve coronary risk factors and to suppress the occurrence of cardiovascular diseases." (PMID 37895151, 2023). "Clinical research has demonstrated that GLP-1R analogs improve the prognosis of cardiovascular disorders by raising the resting heart rate and decreasing arrhythmia in patients with heart failure (HF)." (PMID 37375783, 2023). "In this regard, glucose-lowering drugs, including SGLT2 inhibitors or glucagon-like peptide 1 receptor agonists (GLP-1 RAs) that confer protection against major cardiovascular diseases, are promising for preventing HF in NAFLD or MAFLD." (PMID 36855144, 2023). "The cumulative evidence from the recent cardiovascular outcome trials suggests that the effects of GLP-1R activation have a beneficial effect on blood pressure and cardiovascular diseases." (PMID 34258291, 2021). "Mechanistic and preliminary clinical evidence have consistently pointed toward beneficial effects of GLP-1 analogues and GLP-1R agonists on cardiovascular diseases in T2D patients." (PMID 25338737, 2014). "How do the cardiovascular effects of GLP-1R agonists compare with those of other glucose-lowering therapies or with therapies indicated to treat cardiovascular disease?" (PMID 21167014, 2012). "Additionally, we explore the synergistic effects of combining SGLT2 inhibitors and GLP-1-R agonists in patients with cardiovascular disease." (PMID 37623335, 2023).
cardiovascular disease (continued). "Other than for cardiovascular disease or renal disease, where sodium–glucose cotransporter 2 inhibitors and/or glucagon-like peptide-1 receptor agonists are indicated, the choice of treatment is based upon overall risks of harm or side effect and cost, and not on probable benefit." (PMID 35748917, 2022). "In patients with prior cardiovascular disease, both glucagon-like peptide-1 receptor agonists (GLP-1RA) and sodium–glucose cotransporter 2 inhibitors (SGLT2i) have shown reductions in major adverse cardiac events (nonfatal myocardial infarction, nonfatal stroke and cardiovascular death)." (PMID 35606699, 2022). "In addition, activation of GLP-1R in the brain is albe to reduce appetite, lowering the risks for other diseases such as metabolic and cardiovascular disorders." (PMID 36569936, 2022). "For those at high risk for, or with pre-existing, cardiovascular disease, or with proteinuric kidney disease, there is now strong evidence for treatment escalation with sodium–glucose cotransporter 2 (SGLT2) inhibitors and/or glucagon-like peptide-1 receptor agonists (GLP-1RAs)." (PMID 35748917, 2022). "Abbreviations- CVD: cardiovascular disease; DPP4 inhibitors: dipeptidyl peptidase four inhibitors; GLP1RA: glucagon-like peptide 1 receptor agonist; SGLT2 inhibitors: sodium-glucose cotransporter-2 inhibitors." (PMID 39737272, 2024). "What is the association between high out-of-pocket costs and initiation of a sodium-glucose cotransporter 2 (SGLT2) inhibitor or glucagon-like peptide-1 receptor agonist (GLP-1 RA) among adults with type 2 diabetes and established cardiovascular disease?" (PMID 37307000, 2023). "Among pharmacotherapies aimed at lowering blood glucose levels, glucagon-like peptide 1 receptor agonists (GLP-1RA) represent a class of drugs involved in the improvement of the endothelium damage and the progression of cardiovascular diseases." (PMID 37401947, 2023). "Similarly to SGLT2i, glucagon-like peptide-1 receptor agonists (GLP1-RAs) improve cardiovascular outcomes, especially in metabolic patients, with or without established cardiovascular disease." (PMID 40283534, 2025). "Vascular remodeling is a pathological process in cardiovascular diseases, and GLP-1RAs, including semaglutide, have been shown to reduce vessel remodeling through their anti-inflammatory and anti-proliferative effects independent of their interaction with GLP-1R." (PMID 38500154, 2024).
tumor (100 papers, 2011 to 2026). "There was a significant association between GLP-1R expression and tumor size." (PMID 39908200, 2025). "In conclusion, GLP1R expression levels serve as an important biomarker with potential prognostic significance across multiple cancers, demonstrating both protective and adverse associations depending on the tumor type." (PMID 39777709, 2025). "Similarly, in oncology, semaglutide reprograms tumor-associated macrophages via the GLP-1R/PPARG/ACSL1 pathway, promoting M1 polarization and suppressing tumor progression." (PMID 41226200, 2025). "Certain tumor lineages had a higher proportion of GLP-1R+ cell lines including pancreas (63.6%, n=55), myeloid (60.4%, n=73), peripheral nervous system (60%, n=45), lung (54.9%, n=213), breast (51.4%, n= 70), and lymphoid (37.9%, n=187)." (PMID 41542041, 2026). "When analysing the tumour slices separately for clustering, GLP-1R-positive cells showed significant clustering in all six tumours, with R indices consistently below 1 (P < 0.001)." (PMID 41488993, 2026). "The production of both proteins takes place inside the tumour cells, as insulin transcripts and GLP-1R transcripts are found in the TCGA cohort." (PMID 41488993, 2026). "We next sought to characterize GLP-1R in human TNBCs by immunohistochemical analysis of 100 primary tumor specimens." (PMID 41542041, 2026). "In the tumours, we found that GLP-1R was localized in the cell membrane and insulin in the cytoplasm, as in the pancreatic β-cells, with clusters of GLP-1R-containing cells." (PMID 41488993, 2026). "Most of the tumours contain a few cells with GLP-1R also in the cytoplasm, indicating intracellular synthesis or receptor internalization." (PMID 41488993, 2026). "The expression of GLP-1R we observed in the tumor stroma and immune cells provides a direct conduit for these therapies to influence the local immune environment." (PMID 41542041, 2026). "We obtained GLP-1R transcript data from 182 such tumours from The Cancer Genome Atlas (TCGA) Research Network." (PMID 41488993, 2026). "This approach enabled direct visualization of GLP-1R transcripts (GLP-1R+ cells) within tumor tissue and identification of the specific cell populations expressing them." (PMID 41542041, 2026). "In the tumours, we found that cells expressing insulin were present in the cytoplasm and GLP-1R in the membrane, with a frequency of 2.59 and 1.34%, respectively." (PMID 41488993, 2026). "Together, these results demonstrate that GLP-1 exposure alters the spatial arrangement of cellular neighborhoods within the tumor microenvironment, repositioning GLP-1R+ cells into macrophage-dense and stromal-rich regions." (PMID 41542041, 2026). "Clinically, the high prevalence of GCGR expression in pNET tissues and its inverse correlation with tumour grade, alongside the reduced GLP-1R expression, point to disrupted insulin–glucagon signalling in tumour progression." (PMID 40649254, 2025). "In that study, the investigators noted that they maintained the tirzepatide regimen after tumor implantation to prevent the rapid weight gain that accompanies discontinuation of GLP-1R agonist therapy." (PMID 41178720, 2025). "One limitation of evaluating tumor gene expression of GLP-1R is that many public datasets interrogate tumor core biopsies, which provide samples that contain fibroblasts, immune cells, and vascular cells in addition to malignant cells." (PMID 41178720, 2025). "Preclinical studies of gastrointestinal cancers reinforce the tumor-suppressive effects of GLP-1R therapies." (PMID 41178720, 2025). "To assess the potential effects of semaglutide on PTC cells, we first examined the expression of GLP-1R in 96 pairs of PTC tumor and adjacent normal tissue samples." (PMID 39908200, 2025). "Compared with controls, tumors from exendin-9–treated mice had more infiltrating CD3+ T cells and CD8+ effector memory T cells, supporting a role for GLP-1R activation in modulating the tumor immune environment." (PMID 41178720, 2025).
tumor (continued). "In contrast, patients with high tumor GLP-1R expression in squamous cell carcinomas of cervix or lung, or endometrial carcinoma, had a relatively poor prognosis." (PMID 41178720, 2025). "On the other hand, an animal-based study, in which the GLP-1R antagonist exendin-9 (Ex-9) was delivered into the fourth ventricle of hepatoma tumor-bearing rats, showed that it attenuated the cancer anorexia-cachexia syndrome." (PMID 40364152, 2025). "This case-control study generated several commentary articles, each urging caution when concluding that GLP-1R agonists are tumor-promoting in the thyroid." (PMID 41178720, 2025). "In other tissues, including adrenal, AML, colon, liver, lung, and renal tissues, GLP1R expression remained relatively low in both normal and tumor samples, suggesting a tissue-specific overexpression of GLP1R in certain cancers." (PMID 39777709, 2025). "The subversive loop is influenced by glucagon levels in the tumour and organ microenvironment (TOME), as well as the mutational profile and expression levels of the GCGR and GLP-1R." (PMID 40649254, 2025). "The expression of the GLP-1 receptor (GLP-1R) varies across different tumor types, as well as between healthy and diseased tissues." (PMID 39796190, 2025). "Our study demonstrates that glucagon, through its interaction with GCGR and/or GLP-1R, plays a pivotal role in orchestrating metabolic and adaptive responses in both tumour and normal endocrine cells, particularly under conditions of glucose deprivation." (PMID 40649254, 2025). "We also assessed the protein expression of ANPEP, APOB, and GLP1R in tissues from the primary, tumor, and metastatic groups using IHC staining." (PMID 40696350, 2025). "The results demonstrate a significant reduction in GLP1R expression in tumor tissues compared to normal pancreatic tissues (p = 3.64e-03), with even further downregulation observed in metastatic tissues (p = 8.6e-04)." (PMID 39777709, 2025). "show that bioengineering CAR T cells with GLP-1R agonist and Urolithin A enhances autophagy/mitophagy, leading to improved persistence and anti-tumor activity." (PMID 40107240, 2025). "We examine the role of vitamin D, tumor microenvironment, and GLP-1R agonists in chemoprevention and maintenance therapy." (PMID 40867250, 2025). "This study also demonstrated for the first time that liraglutide suppressed GLP-1R expression in iCCA cells, both in vitro and vivo and incorporated with suppression of iCCA cell migration and reduction of tumor growth in iCCA xenografts." (PMID 38877189, 2024). "The present study was thus carried out to address the roles of GLP-1R and its agonist using in vitro and in vivo models, as well as iCCA tumor tissues obtained from patients in high mortality areas for DM and CCA." (PMID 38877189, 2024). "Fourth, the present study analyzed tumor tissues from patients with iCCA, clinical significance and roles of GLP-1R in extrahepatic CCA need to be warranted." (PMID 38877189, 2024). "The research noted a notable rise in GLP1R messenger RNA (mRNA) levels in EC tissues compared to normal tissues, along with an increase in GLP1R at the protein level in tumor tissues compared to normal tissues." (PMID 39429275, 2024). "In the present study, expression of GLP-1R in tumor tissues is possibly correlated with unfavorable clinical features of iCCA pateints." (PMID 38877189, 2024). "By Reubi and Waser, most GLP-1R-positive tumours showed SSTR2, while the expression of SSTR1, 3, 4 and 5 was lower." (PMID 37894845, 2023). "Concerning PDT requiring high photosensitizer amounts to reach the GLP-1R on the tumor, the use of an antagonist is the rational method to follow." (PMID 37242457, 2023). "A biodistribution of all radiolabelled Ex4 derivatives was conducted in mice carrying subcutaneous CHL GLP-1R positive tumours." (PMID 37665477, 2023).